GDF3 (growth differentiation factor 3)
Diseases named in the same sentence as GDF3 in open-access papers (continued):
Sharing a sentence is not in itself a finding about the gene and the disease.
cancer (9 papers, 2010 to 2025). A tumor composed of atypical neoplastic, often pleomorphic cells that invade other tissues. "The downregulation of Gdf3 and Inpp5j in whole blood might represent a self-protective mechanism against adipogenesis and carcinogenesis, as elevated levels of Gdf3 and Inpp5j are associated with fat deposition and cancer development, respectively." (PMID 39936965, 2025). "Additionally, LEFTY1, LEFTY2, and GDF3 showed higher expression in iPSC lines than in cancer cells and MSC lines." (PMID 39621192, 2025). "Since active BMP signaling in tumors has been proven to be useful for cancer consequences, the GDF3-BMP connection might be investigated in designing new anti-cancer therapeutic modalities." (PMID 37205315, 2023). "Nonetheless, the role of GDF3 in cancer biology remains poorly understood." (PMID 37205315, 2023). "GDF3 is demonstrated as an important player in cancer biology." (PMID 37205315, 2023). "Because GDF3 is highly expressed in the mouse dentate gyrus (a neurogenic area) and previous studies show a role for GDF3 in regulating embryonic and cancer stem cell fate and differentiation we asked whether GDF3 regulates adult neurogenesis." (PMID 27112350, 2016). "Despite its ubiquitous expression the role of GDF3 in cancer remains undetermined." (PMID 20950440, 2010). "Therefore, the present results imply that 12p gains may be indispensable for the development of ECs because 12p includes various genes associated with cancer (e.g., DPPA3, GDF3, KRAS, or CCND2)." (PMID 32999426, 2020). "However, the role of GDF3 in these cancers remains undetermined." (PMID 20950440, 2010). "In addition, proteins of the TGFβ superfamily, GDF3 and GDF11, known to modulate apoptosis in cancer, were also found in the BMSC-EVs." (PMID 36497151, 2022).
infection (4 papers, 2013 to 2024). The state of being infected such as from the introduction of a foreign agent such as serum, vaccine, antigenic substance or organism. "Given that splenic macrophages are critical in dealing with blood-spread infection and activation of immune responses, we lastly focused on evaluating GDF3 expression in macrophages upon LPS challenge." (PMID 31947892, 2020). "In particular, the significant over-expression of the Csf1, Lefty1, Ccrl2, Gdf3, Il-10 and Ccl8 genes (1.8–5.8 fold increases) was seen at day 9 post-infection." (PMID 23861742, 2013).
bacterial infection (1 paper, 2021). "Taken together, these results uncover that GDF3 may represent a novel mediator for controlling bacterial infection." (PMID 33679812, 2021).
connective tissue disorder (1 paper, 2024). A disease involving the connective tissue. "Of the patients without connective tissue disorder-associated symptoms, there was evidence of potential linkage with areas including the GDF3 and GDF6 genes, which encode for growth differentiation factors implicated in Klippel–Feil syndrome, found in 3–5% of the CM1 patients." (PMID 39458107, 2024).
GDF3 also shares sentences with these, for which no sentence is quoted: testicular germ cell tumor (2 papers); type 2 diabetes (2); autoimmune hepatitis (1); carcinoma in situ (1); colon cancer (1); diabetes (1); endotoxemia (1); fibrodysplasia ossificans progressiva (1); germ cell tumor (1); Glucose intolerance (1); hepatitis B virus infection (1); lung carcinoma (1); myeloma (1); neuroblastoma (1); Retinal coloboma (1); thyroid cancer (1).